CD4 (CD4 molecule)
Diseases named in the same sentence as CD4 in open-access papers (continued):
Sharing a sentence is not in itself a finding about the gene and the disease.
HIV-1 infection (continued). "Similarly, another recent study productively analyzed HIV-1-infected primary human CD4 T cells for a comprehensive HML2 loci expression profile, confirming absence of significant differences in the overall HML2 expression upon HIV-1 infection and lack of correlation with HIV-1 expression levels." (PMID 32340287, 2020). "Interestingly, we observed higher early and late HIV-1 RT products upon HIV-1 infection in absence of Vpx (-Vpx) in mitotic cells, which displayed high SAMHD1 pT592-levels (“inf + N”), than compared to CD4+ T cells that entered G1 phase characterized by a reduced pT592 signal (“inf”) (“-Vpx”)." (PMID 29884836, 2018). "Our results showing that HIV-1 infection enhances the transcription and activity of HIF-1α in nonhypoxic conditions raises the hypothesis that a viral component, rather than hypoxia, is responsible for triggering HIF-1α activity in CD4+ T cells." (PMID 30206166, 2018). "Taken together, we hypothesized that Tfh, along with other CD4+ T cell subsets in GALT, would be depleted early in HIV-1 infection and may not be fully reconstituted during ART, which would in turn lead to a deficit of IgA+ B cells, further compromising the integrity of the epithelial barrier." (PMID 27822211, 2016). "While the triazacyclophane scaffold peptide did not affect HIV-1 infection, CD4bs-M was surprisingly found to strongly enhance HIV-1 infection of both CD4 positive and CD4 negative cells, and this effect could be linked to a strong tendency of the peptide to assemble into amyloid fibrils." (PMID 26835447, 2015). "Results showed that Tregs were positive for surface CD4 (i.e., CD4− FOXP3+ cells were absent), indicating that the disappearance of Tregs during the acute phase of infection was not due to surface CD4 down-regulation, but rather to depletion by HIV-1 infection." (PMID 24339781, 2013). "In the present study, we found that the soluble D1D2 molecule could enhance infectivity of a CCR5-using HIV-1 strain Bal in Cf2Th-CCR5 (CD4-/CCR5+) cells at the concentration from 5 to 200 nM, while 2DLT and T1144 exhibited no enhancement of HIV-1 infection at the same concentration range." (PMID 23217195, 2012). "Sufficient memory CD4+ T cells to support a second HIV-1 infection should thus remain in patients infected with a less virulent virus, in patients efficiently controlling their HIV-1 infection (long-term nonprogressors), and in individuals who have started HAART very early in infection." (PMID 17892568, 2007). "Nevertheless, the most significant finding of the current study is that CD73+ memory CD4+ T cells can be infected, but not completely lost in HIV-infection, and instead, during ART, they could represent a particularly refractory reservoir for latent HIV-1 infection." (PMID 33477692, 2021). "While the cell lines used herein are not the natural targets of HIV-1 infection, our results suggest that the in vivo utilization of Nups by HIV-1 and MX2 could vary among cell types (e.g. T cells vs. macrophages or naïve vs. memory vs. effector CD4+ T cells)." (PMID 30084827, 2018). "The depression effect of DDX5 knockdown on p24 production in the presence of wild-type HIV-1 infection is only 30%, which could be due to input of wild-type HIV-1 is relatively high and the knockdown efficiency of DDX5 by exogenous siRNA in primary human CD4+T cells is not good (only ∼27% decrease)." (PMID 23741449, 2013). "Moreover, we demonstrated that GPI-m36.4 could efficiently render human CD4+ T cells (CEMss-CCR5) nonpermissive to both CCR5- and CXCR4-tropic HIV-1 isolates and produced a robust survival advantage in transduced cells compared to unmodified cells during HIV-1 infection." (PMID 33462383, 2021).
viral infection (1,566 papers, 2004 to 2026). "We found that healthy mice harbor T cells with heritable low Pten expression and that monoallelic Pten loss in CD4 T cells causes a bias in their differentiation toward T follicular helper cells during acute viral infection." (PMID 41526572, 2026). "Both populations expressed ADGRG1, which encodes GPR56, a marker of effector memory CD4+ T cells in virus infections and autoimmune diseases." (PMID 40956619, 2025). "In summary, we identify common public TCRs used by immunodominant spike-specific memory CD4+ T-cells, associated with mild disease outcome, which likely play important protective roles to subsequent viral infection events." (PMID 41034205, 2025). "These NKG2A/CD94-expressing CD4+ T cells often exhibit cytotoxic phenotypes or terminal differentiation characteristics and are closely associated with immune exhaustion in various viral infections and autoimmune diseases." (PMID 41328434, 2025). "In summary, viral infection caused significant reductions in all splenic T lymphocyte subsets in chickens, accompanied by marked apoptosis of macrophages, CD4+ T cells, and CD8+ T cells at 4 and 6 hpi." (PMID 41168865, 2025). "Bendamustine can cause prolonged lymphocytopenia, particularly of CD4+ T cells, and has been linked to other viral infections, such as cytomegalovirus." (PMID 41267982, 2025). "Here, MPXV proteins associated with viral infection were analyzed for immunogenic epitopes to design multi-epitope vaccines based on B-cell, CD4+, and CD8+ epitopes." (PMID 40806344, 2025). "In the context of human viral infections, helminth infections like those caused by Ascaris and Trichuris have been linked to higher viral loads and lower CD4+ counts in HIV-infected individuals, complicating HIV management." (PMID 40432048, 2025). "As minimal tissue damage is a hallmark of chronic viral infection, these findings further support evidence that CD4 + cell depletion promotes tissue remodeling processes underlying chronic infection and lasting viral persistence." (PMID 40920821, 2025). "Csf2-/- mice are susceptible to several intracellular bacterial and viral infections in the lung, but a role for GM-CSF in CD4 T cell-mediated immunity to Chlamydia is yet to be established." (PMID 38271477, 2024). "More studies are focused on the mechanism of CD4+T cells in pneumonia caused by viral infection, especially pneumonia caused by SARS-CoV-2." (PMID 39114653, 2024). "Certain viral infections can cause uninfected CD4+ and CD8+ lymphocytes to increase the expression of TRAIL and its receptors, which is subsequently accompanied by a significant reduction in lymphocytes." (PMID 38572318, 2024). "The strong association of the appearance of CD4+ CTLs with viral infections suggests an important role of this subset in antiviral immunity by controlling viral replication and infection." (PMID 38448723, 2024). "We have now established that HIV-1-infected human host CD4+ thymocytes secrete and differentially regulate the host miRNA factors, miR-15a and miR-24, to cause inhibition of differentiation of these virus infection-resistant CD34+ cells in an indirect manner." (PMID 38721526, 2024). "Studies have shown that persistently low CD4+/CD8+ ratios during virus infection are associated with immunosenescence and elevated risks of morbidity and mortality." (PMID 39479205, 2024). "It has been proven that there is severe immune dysfunction in the lungs during measles infection, with a loss of dendritic, CD4+, and NK+ cells and deficient cytokine production which is associated with viral infection." (PMID 39064460, 2024). "Another mechanism would be cell apoptosis, which occurs due to the depletion of CD4 T lymphocytes, brought about by the cytotoxic effect of the viral infection, causing cell death." (PMID 38478483, 2024). "Viral infections cause changes in the number and function of CD4+ T cells and CD8+ T cells in the immune system." (PMID 38313434, 2023).
viral infection (continued). "RyR2 deficiency rendered the CD4+ T cell pool immune suppressive and caused it to behave in the same manner as Foxp3+ Tregs in viral infection, asthma, hypersensitivity, colitis, and tumor development." (PMID 38099494, 2023). "This study further showed that IFN-γ production was significantly reduced in NLRP3-deficient CD4+ T cells during viral infections." (PMID 37799713, 2023). "Nevertheless, it is known that MHC class II deficiency, but not MHC class I deficiency, incapacitates the immune system during viral infection,36which suggests an indispensable role of CD4+ T cells in antiviral immunity." (PMID 37124420, 2023). "Previous research has shown that there are sex variations in susceptibility to a viral infection, which are accompanied by a lower CD4+ T cell mediated response, including expression of IFNγ in female mice." (PMID 37169749, 2023). "Cytotoxic CD4+ T cells have been implicated in host defense against virus infection and tumor cells and in the pathology of various diseases, including fibrotic autoimmune and inflammatory diseases." (PMID 37161048, 2023). "Further studies are required to unveil if the altered CD4/CD8 ratio that we report in progressive IPF is associated with persistent viral infections." (PMID 37762135, 2023). "Aligning with the known susceptibility of CCR5+ CD4 T cells to viral infection and their presence within the CNS, high levels of viral RNA were detected in the brain parenchyma and its border tissues during acute SIV infection." (PMID 38060615, 2023). "Nevertheless, the longevity of protection from viral infections is directly associated with generation of memory B cells together with CD4+ and CD8+ memory T cells." (PMID 36944716, 2023). "In agreement, NAD availability also depends on the de novo synthesis by the tryptophan/kynurenine pathway, whose reduction during viral infection has been associated with exacerbated inflammation and low CD4+ T cell recovery." (PMID 37063865, 2023). "Viral infection is associated with the presence of inflamed and activated hepatic CD4+ T cells expressing cytotoxic molecules." (PMID 37656815, 2023). "To investigate the contribution of CD4 T cells in control of viral infection, we infected CD4 T cell‐deficient mice (MHCII−) with 2 × 105 FFU of ABLV‐luc." (PMID 37767784, 2023). "Further, rs17198965 resides in the binding motif for the transcription factor EZH2, which suppresses major MHC class I molecule expression and is crucial for initiating CD4+ T cell-associated response upon viral infection." (PMID 37415598, 2023). "CD4/CD8 ratio has been used as a quantitative prognostic risk factor in patients with viral infections." (PMID 35814752, 2022). "We investigated the defects in the association of Envs with the CD4, membrane fusion impairment, the cell-to-cell virus transfer, and viral infection capacities." (PMID 35401460, 2022). "HIV infection leads to a depletion of CD4+ T cells which impairs cell-mediated immunity and increases the risk of malignancies such as Kaposi sarcoma (KS) and viral infections such as SARS-CoV-2." (PMID 35935575, 2022). "Enhanced susceptibility to certain virus infection due to pre-existing immunity can occur through mechanisms involving antibodies, activated macrophages, CD4+T-cells, and dendritic cells." (PMID 35558083, 2022). "We find that specific subsets of memory CD4 T cells are highly susceptible to productive viral infection and direct killing." (PMID 35784348, 2022). "Clonal CD8+ T cells are more common than CD4+ T cells and have been associated with responses to common viral infections and tumors." (PMID 36466894, 2022). "Intriguingly, we further observed an enriched quiescence or memory-associated transcriptional profile across most CD4+ T cell subsets responding to chronic viral infection, despite viral load remaining high at this time point." (PMID 36255051, 2022).
viral infection (continued). "Activated CD4+ T cells that express a co-receptor are more susceptible to viral infection and actively produce more virus than quiescent cells, leading to higher viral loads." (PMID 35883501, 2022). "Although rare in the periphery of most healthy individuals, CD4+ TEMRA cells have been identified in the context of viral infections where they are associated with virus control." (PMID 33546283, 2021). "Together these data suggested that loss of Ddb1 in activated CD4+ T cells led to accumulation of DNA damage during acute viral infection." (PMID 34526995, 2021). "Decreases in CD4 T-cell help and increases in antigen levels during viral infection result in increased NCR expression and a hierarchical loss of cytokine production as exhaustion becomes terminal." (PMID 33767694, 2021). "Increased frequencies of CD4+ Tregs have been observed in a huge number of studies on human and animal viral infections and have been associated with the establishment of persistent infection." (PMID 34956200, 2021). "Cd4-/- mice have also been shown to be susceptible to experimental parasitic, bacterial and viral infections." (PMID 34587172, 2021). "Ctrl SMARTA CD4+ T cells exhibited vigorously proliferation post viral infection, whereas METTL3-deficient cells displayed a delayed proliferation." (PMID 33637761, 2021). "The progressive loss of L-selectin expression in infected CD4+ T cells correlated with the viral infection suggesting that the shedding of L-selectin is viral infection-induced." (PMID 34659153, 2021). "For example, the clinical trial of a formalin-inactivated vaccine against RSV in 1967 led to increased mortality in children upon viral infection caused by a type 2 helper CD4+ T cell (Th2) mediated eosinophil invasion of the lungs." (PMID 33414790, 2020). "TCF1 deficiency impaired the generation of all memory CD4 T cells following viral infection, although CXCR5+ TFH memory cells are much more affected than TH1 memory cells." (PMID 32899486, 2020). "Their activation can lead to recruitment of additional macrophages and CD4+ T-cells susceptible to viral infection." (PMID 33117363, 2020). "The infection rate estimated for macrophages, βM, ranges between 4.01 × 10−11 and 1.00 × 10−9 viral RNA copies per μL per day, implying that macrophages are less susceptible to viral infection than CD4+ T cells." (PMID 33211686, 2020). "With EZH2 deficiency-induced inadequate energy support, the CD4 T cell response to acute viral infection is largely diminished." (PMID 32999031, 2020). "IFNγ production by stimulated naive cord blood CD4+ T cells has been measured as 5 to 10-fold less relative to adult CD4+ T cells, resulting in susceptibility to viral infections such as human cytomegalovirus (HCMV) and HIV." (PMID 32499778, 2020). "Although statistically significant, the biological relevance of the minor changes in CD4+ cell counts for mucosal susceptibility to virus infection is most likely negligible, but needs attention in a future clinical trial." (PMID 31792342, 2019). "Infection with LMP1 deficient virus causes similar levels of lymphomagenesis as wild-type virus infection, but tumor formation is abolished after CD4+ T cell depletion." (PMID 31145756, 2019). "It is therefore possible that an early viral infection can prime CD4+ and CD8+ T‐cells, causing increased orexin reactivity, leading to the destruction of the orexin‐producing neurons." (PMID 31730293, 2019). "It is conceivable that other CD4+ CTLs arise in humans and mice under inflammatory conditions during viral infections or in association with autoimmunity." (PMID 31649659, 2019). "In conjunction with telomeric DDR and cell apoptosis, these results suggest that TRF2 protein is inhibited in CD4 T cells by viral infection that is associated with the DDR-mediated cell apoptosis." (PMID 31191531, 2019).
viral infection (continued). "Even though all DCs express the HIV-1-interacting cellular receptor CD4 and the viral coreceptors, being therefore susceptible to viral infection in vitro, infectivity was less prominent than in activated CD4+ T cells." (PMID 31861617, 2019). "The association of CD4 CTLs with virus infection suggests that CD4 CTLs have accumulated in supercentenarians at least partially through clonal expansions triggered by repeated viral exposure." (PMID 31719197, 2019). "While the role of T helper cells in viral infection is not completely understood, the ability of CD4+ T cell to produce cytokines has been linked to protection from lethal infection with VSV." (PMID 31275315, 2019). "CD4 T cell numbers were reduced in 32% of patients and NK cell numbers were reduced in 11% of patients with severe virus infections and PIK3R1 mutations." (PMID 29599765, 2018). "Together, these findings reveal an intimate association between CD4 T cells and homeostasis of functional bTRM to CNS viral infection." (PMID 30372487, 2018). "In the SIV/HIV chimeric SHIV virus infection in macaques, a correlation between apoptosis and CD4 loss is also evident." (PMID 28829402, 2017). "The binding of T-bet to the CNS-34, CNS-22, and CNS+30 enhancer regions of the Ifng locus was increased in Egr2/3-deficient CD4 T cells compared with WT counterparts in response to virus infection." (PMID 28455436, 2017). "While HIV is known to selectively infect CD4 cells, the mechanism of CD4 T cell loss is more complex than virus infection alone." (PMID 28829402, 2017). "Complement-opsonized HIV-1 causes enhanced viral infection of CD4+ T cell lines, PBMCs, monocytes, and macrophages." (PMID 28066413, 2016). "Clinically, there is a clear susceptibility to viral infections and three of the four patients (#2, 3, and 4) have low levels of both IFNγ‐producing NK cells and CD4+ T cells, known to predispose to recurrent and persistent viral infection." (PMID 27896283, 2016). "Having generated confidence in MEF-2 involvement in HTLV-1 pathogenesis, we proceeded to understand the underlying molecular interactions in the context of primary CD4+ T cells and viral infection." (PMID 25809782, 2015). "In mice, relative stability of CD4+ memory T cells specific for lymphocytic choriomeningitis virus has been observed following multiple heterologous virus infections, despite the parallel loss of lymphocytic choriomeningitis virus-specific CD8+ memory T cells." (PMID 26332995, 2015). "An association between non-R5 virus infection and more rapid CD4 T-cell loss both in treated and ART-naive subjects has been reported." (PMID 25888743, 2015). "Enforced expression of BCL6 in EGR2/3-deficient CD4 T cells partially restored Tfh differentiation and GC formation in response to virus infection." (PMID 25979336, 2015). "While CD4 cells are clearly implicated in the control of chronic viral infections, the co-stimulatory signals that contribute to CD4 T cell help remain poorly defined." (PMID 25590581, 2015). "CD4 T cell exhaustion is a hallmark of persistent viral infections so we sought to determine if these TH1 cells maintained antigen-responsiveness." (PMID 23754944, 2013). "Our results are consistent with previous reports showing that the differential susceptibility in naïve and memory CD4+ T cells can already be detected during the initial stages of viral infection such as viral entry or DNA synthesis." (PMID 24244453, 2013). "In contrast to patients with compromised CD8 T cell functions, the susceptibility to viral infections, especially infections with the herpes virus family, was increased in patients with CD4 T cell deficiencies." (PMID 23717308, 2013). "Evidence for a direct antiviral function of CD4 T cells during persistent viral infections comes from studies in CD4 T cell-deficient or compromised hosts." (PMID 23717308, 2013).